RN7SL583P (RNA, 7SL, cytoplasmic 583, pseudogene)
Gene: Miscellaneous RNA gene on chromosome 1 (88,477,828 to 88,478,114, reverse strand). Ensembl gene ENSG00000239504.
Homologues: Orthologues: chimpanzee Metazoa_SRP (99% identical), macaque Metazoa_SRP (88% identical). Paralogues in human: RN7SL2 (83% identical), RN7SL1 (82% identical), RN7SL3 (82% identical), RN7SL357P (80% identical), RN7SL786P (80% identical), RN7SL166P (79% identical), RN7SL444P (79% identical), RN7SL220P (79% identical), RN7SL709P (79% identical), RN7SL147P (79% identical), RN7SL566P (79% identical), RN7SL126P (78% identical), and 706 more.